POLR1G (RNA polymerase I subunit G)
Description:
Component of RNA polymerase I (Pol I), a DNA-dependent RNA polymerase which synthesizes ribosomal RNA precursors using the four ribonucleoside triphosphates as substrates. Involved in UBTF-activated transcription, presumably at a step following PIC formation. [Isoform 2]: Has been described as a component of preformed T-cell receptor (TCR) complex.
Synonyms: ASE-1; ASE1; CAST; CD3EAP; PAF49; RPA34; A34.5
Tractability: Small molecule: a structure with a bound ligand is known. PROTAC: UniProt records ubiquitination sites on it; ubiquitination databases record sites on it.
Safety:
Unwanted effects reported when the protein is acted on. In parentheses: how it was acted on, where the effect was seen, and who reports it.
mucositis (source: ClinPGx)
nephrotoxicity (source: ClinPGx)
neuropathy (source: ClinPGx)
neutropenia (source: ClinPGx)
side effects (source: ClinPGx)
vomiting (source: ClinPGx)
Gene: Protein-coding gene on chromosome 19 (45,406,644 to 45,410,737, forward strand). Ensembl gene ENSG00000117877.
Subcellular location: Nucleus, nucleolus; Chromosome
Subcellular location (Human Protein Atlas): Nucleoli fibrillar center; Nucleoplasm; Mitochondria
Pathways (Reactome):
Gene expression (Transcription): B-WICH complex positively regulates rRNA expression; NoRC negatively regulates rRNA expression; RNA Polymerase I Promoter Escape; RNA Polymerase I Transcription Initiation; RNA Polymerase I Transcription Termination
Gene Ontology:
Molecular function: protein binding; RNA binding
Biological process: transcription elongation by RNA polymerase I; transcription initiation at RNA polymerase I promoter; cell surface receptor protein tyrosine kinase signaling pathway; nucleolar large rRNA transcription by RNA polymerase I; rRNA transcription; termination of RNA polymerase I transcription; transcription by RNA polymerase I
Cellular component: fibrillar center; nucleoplasm; RNA polymerase I complex; nucleolus; nucleus; RNA polymerase I transcription regulator complex; chromosome
Genetic constraint (gnomAD): Loss-of-function variants: 12 observed, 8.55 expected, observed/expected ratio (o/e) 1.4, 90% interval 0.88 to 1.91. That is too few expected variants to judge how well the gene tolerates losing a copy. Missense variants: 614 observed, 660.15 expected, observed/expected ratio (o/e) 0.93, 90% interval 0.87 to 0.99. Synonymous variants: 248 observed, 268.22 expected, observed/expected ratio (o/e) 0.92, 90% interval 0.83 to 1.03.
Homologues: Orthologues: chimpanzee POLR1G (99% identical), macaque POLR1G (90% identical), pig POLR1G (63% identical), guinea pig POLR1G (63% identical), dog POLR1G (62% identical), rat Polr1g (50% identical), mouse Polr1g (45% identical), zebrafish polr1g (15% identical), tropical clawed frog polr1g (12% identical).
Diseases named in the same sentence as POLR1G in open-access papers:
POLR1G is named in the same sentence as 19 diseases in open-access papers, as found by Europe PMC text mining. Sharing a sentence is not in itself a finding about the gene and the disease. The quoted sentences say what the papers report.
lung carcinoma (10 papers, 2008 to 2024). "We previously reported that PPP1R13L rs1970764, POLR1G rs967591 and rs735482 were associated with lung cancer or interacted in relation to lung cancer risk among both Caucasian Danes and Chinese15–18." (PMID 37147350, 2023). "Special interactions between smoking duration, IL1B rs3136558 and POLR1G rs967591; smoking-duration, IL1B rs1143633, rs3136558 and rs1143630; and IL1B rs1143633, PPP1R13L rs1970764 and POLR1G rs735482 were observed in relation to lung cancer risk." (PMID 37147350, 2023). "And we assessed gene–gene or gene–gene–environment interactions between genes of pathway of cytokines and inflammatory response and gene expression (transcription) pathway related to lung cancer risk, including the interaction between IL1B htSNPs, PPP1R13L and POLR1G risk SNPs and smoking-duration." (PMID 37147350, 2023).
POLR1G also shares sentences with these, for which no sentence is quoted: cancer (10 papers); tumor (7); non-small cell lung carcinoma (3); xeroderma pigmentosum (3); colorectal cancer (2); endometrial cancer (2); breast carcinoma (1); cancer of the skin (1); cardiovascular diseases (1); cervical cancer (1); lung squamous cell carcinoma (1); multiple myeloma (1); poisoning (1); rectal cancer (1); Sleep apnea (1); xeroderma pigmentosum group B (1); xeroderma pigmentosum group C (1); xeroderma pigmentosum group F (1).